JAK2 (Janus kinase 2)
Diseases named in the same sentence as JAK2 in open-access papers (continued):
Sharing a sentence is not in itself a finding about the gene and the disease.
erythrocytosis (continued). "However, the facts that polycythemia induced in mice by JAK2 V617F is polyclonal and manifested immediately following engraftment argue that JAK2 V617F is both necessary and sufficient for this phenotype." (PMID 17183644, 2006). "Here, we have demonstrated that JAK2 V617F induces the complete spectrum of the clinicopathological features of human PV in mice, including polycythemia due to overproduction of erythrocytes, increased red cell mass, low plasma Epo levels, and presence of EEC in BM and spleen." (PMID 17183644, 2006). "To discover genetic variants in unexplained erythrocytosis, we performed whole exome sequencing in 27 patients with JAK2-negative polycythemia after excluding the presence of any mutations in genes previously associated with erythrocytosis (EPOR, VHL, PHD2, EPAS1, HBA, and HBB)." (PMID 37428608, 2023). "It revealed a frequent association between the JAK2 GGCC haplotype, a germline combination of single nucleotide polymorphisms (SNPs) and a CALR SNP (rs1049481, G > T) with an unknown biological significance in cases of erythrocytosis." (PMID 37239426, 2023). "However, we can rule out the possibility that the Jak2-associated polycythemia was responsible for aortic dilation in mutant mice since aortopathy was observed in Jak2V617FPf4 mice before polycythemia developed." (PMID 36329047, 2022). "Therefore, many JAK2 negative erythrocytosis patients with erythrocytosis and with no apparent secondary cause for erythrocytosis do not have an adequate follow-up." (PMID 34013406, 2021). "Additionally, patients with erythrocytosis for whom secondary factors have already been ruled out should be tested for the JAK2 mutation if possible to confirm the PV diagnosis." (PMID 28877745, 2017). "In our model, robust polycythemia is induced by modest overexpression of JAK2 V617F in BM with two normal JAK2 genes, but further studies will be necessary to determine whether the phenotype is influenced by levels of normal JAK2." (PMID 17183644, 2006). "However, in the family studied, the co-segregation of the JAK2 E846D variant with erythrocytosis was restricted to a nuclear family in which the non-affected sibling could not be tested." (PMID 37239426, 2023). "We report a case of erythrocytosis as the primary manifestation of a chronic myeloid leukemia, with the presence of the Philadelphia chromosome and the Breakpoint cluster region-Abelson murine leukemia viral oncogene homolog 1 fusion gene, and in the absence of any Janus kinase 2 mutation." (PMID 26187587, 2015). "Had our study cohort been screened with EPO-JAKPOT, we would have ruled out JAK2-positive erythrocytosis in 130 patients (55%) without molecular testing at the cost of only 2 missed cases (1%)." (PMID 40806795, 2025). "In summary, the EPO-JAKPOT score shows potential for excluding JAK2 mutant erythrocytosis in select patients without molecular testing." (PMID 40806795, 2025). "In the JAKPOT derivation study, the absence of all three criteria ruled out JAK2 mutant erythrocytosis with a sensitivity of 95–100% and a false negative rate of 0.4%, but the score has not been externally validated." (PMID 40806795, 2025). "In a murine model of JAK2 p.V617F-driven PV, genetic deletion or pharmacologic inhibition of OSM reduced polycythemia, spleen size, BM fibrosis and the levels of proinflammatory cytokines, establishing OSM as a critical mediator of oncogene-induced inflammation and immune suppression." (PMID 41372120, 2025). "The NGS panel should include all coding exons of the JAK2 and MPL genes, as rare non-canonical driver mutations can be detected in both MPN and constitutional thrombocythemia/polycythemia." (PMID 39903357, 2025). "Elevated EPO (>16.9 mU/mL) had a Sn of 0.16 (95% CI, 0.11–0.22), Sp of 1.0 (95% CI, 0.91–1.0), −LR of 0.84, and an infinite +LR for the diagnosis of JAK2 negative (secondary) erythrocytosis." (PMID 40806795, 2025).
erythrocytosis (continued). "The fact that diagnosis of JAK2‐negative PV essentially depends on bone marrow pathology makes differentiating between JAK2‐negative PV, relative erythrocytosis, and idiopathic erythrocytosis difficult." (PMID 35775283, 2023). "The majority of patients were males (32/34, 94%) which is in line with previous studies showing that males suffer more from JAK2 negative polycythemia." (PMID 34946900, 2021). "In rare instances, SH2B3/LNK exon 2 mutations or polymorphisms have been reported in patients with unexplained erythrocytosis, with subnormal serum EPO levels, and absence of JAK2, MPL, and EPOR mutations." (PMID 34021251, 2021). "While NGS confirmed the absence of the JAK2 V617F and exon 12 mutations, several alternative mutations of JAK2 have been identified in sporadic cases of “PV-like” MPN and hereditary erythrocytosis, yet none were identified by NGS in exons 12–15 in the patient." (PMID 29682367, 2018). "This suggests that compensation by other Src family members is unlikely to play a role in polycythemia induced by JAK2 V617F in these mutant cells." (PMID 17183644, 2006). "To investigate the role of Src kinases in the polycythemia induced by JAK2 V617F, we employed donor mice lacking Lyn, Hck, and Fgr, the three principal Src kinases in myeloerythroid progenitor cells, as BM donors for transduction with JAK2 V617F." (PMID 17183644, 2006). "Likewise, high EPO (>16.9 mU/mL) had high specificity (1.0; 95% CI 0.89–1.0) but low sensitivity (0.16; 95% CI, 0.11–0.21) for JAK2-negative (secondary) erythrocytosis." (PMID 40806795, 2025). "A previous report of Mpl−/−;JAK2-V617F mutant mice utilised a model without erythrocytosis." (PMID 38491305, 2024). "When the myeloid NGS panel and JAK2 are both negative, the detection of mutations in other genes via germline NGS panels may be useful to diagnose hereditary erythrocytosis." (PMID 36611899, 2022). "However, dual targeting of JAK2 and ERK1/2 via genetically induced ERK1/2 deficiency enhanced reduction of erythrocytosis in Jak2V617F settings, while no cytopenia occurred." (PMID 34480104, 2021). "Thus, erythropoiesis driven by JAK2V617F results in polycythemia that requires a spleen, while erythropoiesis driven by wild type JAK2 does not." (PMID 19789710, 2009). "The results demonstrate that these particular Src kinases are not required for polycythemia induced by JAK2 V617F, and might even play a negative role in JAK2 V617F signaling." (PMID 17183644, 2006). "Despite the marked polycythemia, the MPD induced by JAK2 V617F was non-fatal in both strains, with recipients surviving for many months." (PMID 17183644, 2006). "However 1% of patients with PV are JAK2 negative, as the EPO level is not suppressed in 20% of cases, and the BM does not show panmyelosis in 10% of JAK2-positive erythrocytosis." (PMID 36611899, 2022).
glioma (87 papers, 2011 to 2026). A benign or malignant brain and spinal cord tumor that arises from glial cells (astrocytes, oligodendrocytes, ependymal cells). "Our study shows that overexpression of KIAA0040 is linked to glioma malignancy through the JAK2/STAT3 pathway." (PMID 38661644, 2024). "JAK2 plays a central role in phosphorylation of glioma-associated STAT3, a key component of the PI3K-signaling pathway." (PMID 34359681, 2021). "Of the targets identified, PI3K and JAK2 were prioritized based on their elevated expression in glioma datasets from TCGA." (PMID 41270054, 2025). "Collectively, these results indicated that NIBAN2 triggered glioma progression by stimulating the JAK2/STAT3/c‐Myc signaling pathway." (PMID 40944417, 2025). "It is noteworthy that, in contrast to the positive regulatory role of USP38 in malignancies such as gastric and colorectal cancers, USP38’s suppression of JAK2/STAT3 signaling pathway activation in glioma demonstrates its dual role in tumor regulation." (PMID 40936898, 2025). "Glioma-released exosomal miR-3591-3p promotes macrophage to the M2 phenotype by targeting CBLB to activate the JAK2/PI3K/Akt/mTOR and STAT3, thereby promoting glioma progression." (PMID 40443670, 2025). "IL-6 can bind to IL-6R on the surface of glioma cells and activate the downstream JAK2/STAT3 signaling pathway, enabling them to acquire the stemness and invasiveness phenotype." (PMID 40243478, 2025). "Functional assays showed that NIBAN2 enhanced glioma cell aggressiveness by activating JAK2/STAT3 signaling and promoted tumor growth by preventing apoptosis and accelerating the cell cycle." (PMID 40944417, 2025). "Other BPAs, like CHE, inhibit non-small cell lung cells by downregulating β-Catenin, while NTD suppresses epithelial mesenchymal transformation and glioma stem cells by targeting the JAK2/STAT3 signaling pathway." (PMID 40630130, 2025). "Mechanistically, HIF‐1α targeted NIBAN2 to upregulate it, thereby promoting glioma progression by stimulating the JAK2/STAT3/c‐Myc signaling axis." (PMID 40944417, 2025). "Astrocyte-derived CCL2 can bind CCR2 on glioma cells to maintain stemness characteristics by activating JAK2/STAT3-Notch signaling pathway." (PMID 40243478, 2025). "Nuclear-localized SIRT6 is notably downregulated in glioma and acts as a tumor suppressor through various mechanisms, including inhibition of the JAK2/STAT3 and NOTCH3 signaling pathways." (PMID 40710366, 2025). "Mechanistic studies indicate that B7-H3 promotes glioma cell proliferation and invasion via the JAK2/STAT3/Slug pathway and by inducing epithelial–mesenchymal transition (downregulating E-cadherin and upregulating MMP-2/9)." (PMID 40867203, 2025). "Consistently, we demonstrate that KIAA0040 overexpression promotes glioma cell migration and invasion, which is possibly mediated via the JAK2/STAT3 pathway activation." (PMID 38661644, 2024). "SRPK1 promotes the proliferation, migration, and invasion of gliomas by activating the Wnt/β-catenin and JAK-2/STAT-3 signaling pathways." (PMID 38397980, 2024). "Studies had shown that inhibiting of the IL-6/JAK2/STAT3 signaling pathway inhibited the proliferation of glioma cells and promotes apoptosis." (PMID 37642814, 2024). "SRPK1 promotes the proliferation, migration, and invasion of gliomas through the activation of the Wnt/β-catenin and JAK-2/STAT-3 signaling pathways." (PMID 38397980, 2024). "Altogether, our results indicate that KIAA0040 promotes glioma cell migration and invasion through the JAK2/STAT3 pathway activation." (PMID 38661644, 2024). "By blocking JAK2, resveratrol can potentially reduce glioma cell proliferation and induce apoptosis." (PMID 39769099, 2024). "Overexpression of SRPK1 activates the Wnt/β-catenin (wingless-int1/β-catenin) and JAK-2/STAT-3 (Janus kinase 2/signal transducer and activator of transcription 3) signaling pathways, promoting the proliferation, migration, and invasion of gliomas." (PMID 38397980, 2024).
glioma (continued). "Functional assays showed that KIAA0040 enhances glioma growth, migration and invasion by activating the JAK2/STAT3 pathway." (PMID 38661644, 2024). "SRPK1 regulates the proliferation, invasion, and migration of glioma cells through the Wnt/β-catenin/JAK-2/STAT-3 pathway." (PMID 38397980, 2024). "In vitro experiment showed that ARSD can promote glioma cell proliferation through JAK2/STAT3 pathway and regulate M2 macrophage infiltration." (PMID 37766864, 2023). "TRPM7 activates the JAK2/STAT3 signaling pathway leading to glioma aggravation, as there is crosstalk between this pathway and ALDH1 and CD133, two glioma stemness markers, suggesting a role of TRPM7 in glioma stem cells." (PMID 37762011, 2023). "With the combination of bioinformatic analysis and experimental validation, we identified that ARSD can promoted glioma progression by regulating JAK2/STAT3 pathway and M2 macrophage infiltration." (PMID 37766864, 2023). "Using CCK-8 and Transwel, we found the increased proliferation, migration, and invasion of glioma cells induced by ARSD overexpression were reversed upon inhibition of the JAK2/STAT3 signaling pathway with AG490." (PMID 37766864, 2023). "High level of ARSD promoted the development of glioma by regulating M2 macrophage infiltration and JAK2/STAT3 pathway." (PMID 37766864, 2023). "Combined with cell experiment and bioinformatic analysis, we found that ARSD can promote glioma progression through regulation of JAK2/STAT3 pathway and M2 macrophage infiltration." (PMID 37766864, 2023). "A recent study reported that Fraxetin inhibits proliferation and metastasis of glioma cells by inactivating JAK2/STAT3 signaling." (PMID 35387563, 2022). "They further revealed that B7-H3 induces glioma invasion through the JAK2/STAT3/Slug/MMP-2/-9 pathway and is involved in epithelial‐mesenchymal transition (EMT)." (PMID 36284349, 2022). "SIRT6 suppresses the oxidative stress response while inhibiting Janus kinase 2 (JAK2)/STAT3 signaling pathway activation during glioma treatment." (PMID 35935861, 2022). "As the cluster keyword, STAT3 and its related pathways like JAK2/STAT3 pathway are widely researched in gliomas." (PMID 36338770, 2022). "To further verify the inhibitory effect of fraxetin on the JAK2/STAT3 signaling pathway in glioma, we conducted experiments with the activator of JAK2/STAT3 pathway, Colivelin TFA." (PMID 33959183, 2021). "Collectively, our study confirmed that sorafenib enhanced the temozolomide sensitivity of human glioma cells through oxidative stress-mediated autophagy and JAK2/STAT3-AIF axis." (PMID 34277607, 2021). "NC also inhibited relevant glioma stem‐like cell‐related markers through its effects on the JAK2/STAT3 pathway." (PMID 33788424, 2021). "The combination of sorafenib and TMZ significantly decreased the expression of phosphorylated JAK2 in U251 glioma cells." (PMID 34277607, 2021). "To further demonstrate how ELK3 regulates these pathways to affect the malignant progression of gliomas, we explored the regulation of JAK2/STAT3 by ELK3 through western blot experiments." (PMID 34976781, 2021). "In conclusion, our results demonstrate that NC effectively inhibits the EMT process and cancer stem cell‐like properties in glioma cells and these effects of NC were achieved via JAK2/STAT3 signaling." (PMID 33788424, 2021). "In vitro experiments reveal that ELK3 overexpression can increase the proliferation and migration of gliomas cells and play a role through the regulation of JAK2 the STAT3 signaling pathway." (PMID 34976781, 2021). "The results indicate that sorafenib enhanced the temozolomide sensitivity of human glioma cells by inducing oxidative stress-mediated autophagy and JAK2/STAT3-AIF axis." (PMID 34277607, 2021). "Our results suggested that fraxetin not only inhibits the proliferation, invasion, and migration of glioma but also induces glioma cells apoptosis by suppressing activation of JAK2/STAT3 signaling pathway." (PMID 33959183, 2021).
glioma (continued). "Increasing evidence shows that the activation of IL6-mediated JAK2/STAT3 signaling is frequently associated with glioma, and promotes the cell growth, proliferation, and invasion of glioma cells." (PMID 33858489, 2021). "Previous studies have shown that B7-H3 overexpression can promote the occurrence of EMT in gliomas through the JAK2/STAT3/Slug signaling pathways." (PMID 34970415, 2021). "We detected the effect of NC on JAK2/STAT3 signaling by western blot analysis of related proteins in NC‐treated glioma cells." (PMID 33788424, 2021). "In glioma stem cells, circATP5B competitively sponges miR-185-5p, upregulating the expression of the homeobox gene HOXB5, which induces the proliferation of glioma stem cells through JAK2/STAT3 signaling." (PMID 34439740, 2021). "In conclusion, our study confirmed that sorafenib enhanced the temozolomide sensitivity of human glioma cells through oxidative stress and JAK2/STAT3 signaling pathway inhibition." (PMID 34277607, 2021). "It has been reported that STAT3 can be activated by Janus-activated kinases (JAKs) and c-Src, thus, we evaluated the expression levels of JAK2 and Src in glioma cells after incubation with β-elemene by western blot analysis." (PMID 34257541, 2021). "AG490 is a Janus Kinase 2 (JAK2) inhibitor used for glioma therapy, but it also has inhibitory activity toward the epidermal growth factor receptor (EGFR) mediating PI3K/AKT signaling." (PMID 33172406, 2020). "AP-2α functions as a novel tumor suppressor to inhibit the stemness of glioma cancer cells by inhibiting the Nanog/Sox2/CD133 regulatory axis and decreasing the resistance of glioma cells to TMZ by blocking the IL6/Jak2/STAT3 signaling pathway." (PMID 31534499, 2019). "Recent evidence reported that cAMP/PKA enhances IL-1β induced-IL-6 synthesis through Jak2/Stat3 activation, identifying novel therapeutic targets for the treatment of glioma." (PMID 28157712, 2017). "Role of JAK2 in Hormone-like Cytokine Signaling stood out because GHR (growth hormone receptor) and IRS1 (insulin receptor substrate 1) has been linked with glioma progression." (PMID 27669421, 2016). "Importantly, SIRT6 overexpression inhibits the activation of the JAK2/STAT3 (Janus kinase 2/signal transducer and activator of transcription 3) signaling pathway, which is often overactive in gliomas, contributing to the anti-cancer effects of SIRT6." (PMID 40710366, 2025). "Furthermore, high expression of SRPK1 in glioma tissues often correlated with high expression of β-catenin and p-JAK2." (PMID 38397980, 2024). "Furthermore, ARSD serves as a prognostic biomarker that facilitates the progression of glioma cells via the activation of the JAK2/STAT3 signaling pathway and infiltration of M2 macrophages." (PMID 38895621, 2024). "Collectively, our results confirmed that IGF2BP3/circGNB1/miR-515-5p/miR-582-3p/XPR1 axis could promote tumorigenesis and malignant progression of glioma via IL6/JAK2/STAT3 signaling pathway." (PMID 37407973, 2023). "Phosphorylation of STAT3 and JAK2 was significantly enhanced in glioma cells, and inhibition of IL-6/JAK2/STAT3 signaling pathway could significantly inhibit the proliferation of glioma cells and promote cell apoptosis." (PMID 36591515, 2022). "In glioma, JAK2/STAT3 signaling may regulate the expression of E‐cadherin, N‐cadherin, vimentin, and β‐catenin via related transcription factors to inhibit the EMT process." (PMID 33788424, 2021). "Considering the observed overactivation of JAK2/STAT3 in glioma, we speculated that fraxetin might have an inhibitory effect on glioma development via suppressing JAK2/STAT3 activity." (PMID 33959183, 2021). "In addition, stress-induced phosphoprotein 1 (STIP1) secreted by TAMs induces proliferation of glioma cells in vitro, while IL-10 was shown to promote glioma cell proliferation via JAK2/STAT3 signaling in a glioma model." (PMID 34503065, 2021).